SLC8B1 (solute carrier family 8 member B1)
Description:
Mitochondrial sodium/calcium antiporter that mediates sodium-dependent calcium efflux from mitochondrion, by mediating the exchange of 3 sodium ions per 1 calcium ion. Plays a central role in mitochondrial calcium homeostasis by mediating mitochondrial calcium extrusion: calcium efflux is essential for mitochondrial function and cell survival, notably in cardiomyocytes (By similarity). Mitochondrial calcium export is ph-dependent (By similarity). Regulates rates of glucose-dependent insulin secretion in pancreatic beta-cells during the first phase of insulin secretion: acts by mediating efflux of calcium from mitochondrion, thereby affecting cytoplasmic calcium responses. Required for store-operated Ca(2+) entry (SOCE) and Ca(2+) release-activated Ca(2+) (CRAC) channel regulation: sodium transport by SLC8B1 leads to promote calcium-shuttling that modulates mitochondrial redox status, thereby regulating SOCE activity. Involved in B-lymphocyte chemotaxis (By similarity). Able to transport Ca(2+) in exchange of either Li(+) or Na(+), explaining how Li(+) catalyzes Ca(2+) exchange. In contrast to other members of the family its function is independent of K(+).
Synonyms: NCKX6; NCLX; SLC24A6; FLJ22233
Tractability: Antibody: its Gene Ontology location is reachable by antibodies, with high confidence; UniProt predicts a signal peptide or a membrane-spanning region. PROTAC: ubiquitination databases record sites on it; a small molecule that binds it is known.
Target class: SLC08 family of sodium/calcium exchangers; SLC superfamily of solute carriers; Transporter; Electrochemical transporter
Gene: Protein-coding gene on chromosome 12 (113,298,759 to 113,359,502, reverse strand). Ensembl gene ENSG00000089060.
Subcellular location: Mitochondrion inner membrane
Pathways (Reactome):
Transport of small molecules: Mitochondrial calcium ion transport; Sodium/Calcium exchangers
Gene Ontology:
Molecular function: calcium:sodium antiporter activity; protein homodimerization activity; calcium:monoatomic cation antiporter activity; calcium:sodium antiporter activity involved in regulation of cardiac muscle cell membrane potential; identical protein binding
Biological process: calcium export from the mitochondrion; glucose homeostasis; mitochondrial calcium ion homeostasis; mitochondrial calcium ion transmembrane transport; regulation of cardiac muscle cell membrane potential; regulation of cytosolic calcium ion concentration; regulation of insulin secretion; regulation of store-operated calcium entry; calcium ion transmembrane transport; intracellular calcium ion homeostasis; regulation of lymphocyte chemotaxis; sodium ion transmembrane transport; transmembrane transport
Cellular component: mitochondrial crista; mitochondrial inner membrane; mitochondrial membrane; mitochondrion; plasma membrane; membrane; sarcolemma
Genetic constraint (gnomAD): Loss-of-function variants: 53 observed, 66.65 expected, observed/expected ratio (o/e) 0.8, 90% interval 0.64 to 1. The upper end of that interval is the gene's LOEUF score, 1, which puts it in group 4 of 6, group 1 being the genes least tolerant of losing a copy. Missense variants: 657 observed, 767.69 expected, observed/expected ratio (o/e) 0.86, 90% interval 0.8 to 0.91. Synonymous variants: 336 observed, 332.73 expected, observed/expected ratio (o/e) 1.01, 90% interval 0.92 to 1.11.
Homologues: Orthologues: chimpanzee SLC8B1 (99% identical), macaque SLC8B1 (96% identical), pig SLC8B1 (88% identical), mouse Slc8b1 (83% identical), rat Slc8b1 (83% identical), guinea pig SLC8B1 (82% identical), rabbit SLC8B1 (76% identical), tropical clawed frog slc8b1 (60% identical), dog SLC8B1 (57% identical), Caenorhabditis elegans ncx-7 (31% identical), Caenorhabditis elegans ncx-6 (29% identical), Caenorhabditis elegans ncx-9 (29% identical), and 7 more.
Diseases named in the same sentence as SLC8B1 in open-access papers:
SLC8B1 is named in the same sentence as 49 diseases in open-access papers, as found by Europe PMC text mining. Sharing a sentence is not in itself a finding about the gene and the disease. The quoted sentences say what the papers report.
amyloidosis (5 papers, 2019 to 2025). A disorder characterized by the localized or diffuse accumulation of amyloid protein in various anatomic sites. "At the same time, neuronal deletion of the mitochondrial Na+/Ca2+ exchanger (NCLX, Slc8b1 gene) accelerated memory decline and increased amyloidosis, tau pathology, and, ultimately, memory loss in 3XTg-AD mice." (PMID 36233148, 2022). "Recent results by Jadiya and colleagues demonstrate that neuronal deletion of the mitochondrial Na+/Ca2+ exchanger in 3xTg-AD mutant mice (NCLX, Slc8b1 gene) accelerated memory decline and increased amyloidosis and tau pathology." (PMID 32012922, 2020). "Neuronal deletion of the mitochondrial Na+/Ca2+ exchanger (NCLX, Slc8b1 gene) accelerated memory decline and increased amyloidosis and tau pathology." (PMID 31467276, 2019).
Alzheimer disease (4 papers, 2019 to 2025). A progressive, neurodegenerative disease characterized by loss of function and death of nerve cells in several areas of the brain leading to loss of cognitive function such as memory and language. "Remarkably, a recent analysis of mitochondrial Ca2+-related genes in 25 publicly available microarray and RNA-Sequencing datasets revealed a significant upregulation of Na+/Ca2+ exchanger-encoding gene SLC8B1 in Alzheimer’s disease patients when compared to age-matched healthy individuals." (PMID 32580385, 2020). "Along these lines, upregulating the expression level of SLC8B1 gene rescued mitochondrial Ca2+-induced pathology in 3xTg Alzheimer’s disease mouse model." (PMID 32580385, 2020).
Intellectual disability (4 papers, 2021 to 2025). "A recent study has reported that a human recessive missense mutation in the gene encoding NCLX, SLC8B1, impairs its function and is associated with severe intellectual disability." (PMID 36760367, 2023).
colon cancer (3 papers, 2017 to 2024). "Interestingly, we found that SLC8B1 mRNA level was significantly reduced in colon cancer." (PMID 39006025, 2024).
cardiomyopathies (1 paper, 2021). "We identified a loss of function variant of the human SLC8B1 gene (NCLXP367S) in a Pakistani family in which the affected individuals exhibit severe mental retardation and cardiomyopathies, consistent with dysregulation of calcium dynamics in the brain and heart." (PMID 34079053, 2021).
colorectal tumors (1 paper, 2020). "Here, we demonstrate decreased expression of the mitochondrial Na+/Ca2+/Li+ exchanger NCLX (SLC8B1) in human colorectal tumors and its association with advanced-stage disease in patients." (PMID 32914752, 2020). "Consistent with the TCGA data, we observed a substantial reduction to a near loss in SLC8B1 mRNA in colorectal tumor samples isolated from patients undergoing surgery at Penn State University Medical Center as compared to the paired normal adjacent tissues." (PMID 32914752, 2020). "There was a significant reduction in SLC8B1 mRNA level in late-stage (stage III and IV) colorectal tumors as compared to early-stage (stages I and II) tumors from the TCGA database, with similar results when we analyzed the patient samples obtained from Penn State University Medical Center." (PMID 32914752, 2020).
mucinous adenocarcinoma (1 paper, 2020). An invasive adenocarcinoma composed of malignant glandular cells which contain intracytoplasmic mucin. "Both adenocarcinoma and mucinous adenocarcinoma had a significant reduction in SLC8B1 mRNA levels as compared to the normal tissue." (PMID 32914752, 2020).
pancreatic ductal adenocarcinoma (1 paper, 2021). An infiltrating adenocarcinoma that arises from the epithelial cells of the pancreas. "ENST00000587299.1 and ENST00000553238.5 participated in the transcription of gene SLC8B1 and ATP6V0A1 that was associated with the invasive process of oral tongue cancer and pancreatic ductal adenocarcinoma, respectively." (PMID 34094912, 2021).
rectal adenocarcinoma (1 paper, 2020). "Using the publicly available Cancer Genome Atlas (TCGA) database, we found that NCLX (SLC8B1) mRNA levels were significantly downregulated in both colon and rectal adenocarcinoma (COADREAD) tumors as compared to the adjacent normal tissue." (PMID 32914752, 2020). "(A) TCGA data analysis showing SLC8B1 mRNA levels in tumor tissues and adjacent normal tissues of COADREAD (colon and rectal adenocarcinoma) patients." (PMID 32914752, 2020).
cancer (9 papers, 2018 to 2025). A tumor composed of atypical neoplastic, often pleomorphic cells that invade other tissues. "There are no data in cancer studies concerning SLC8B1 (encoding NCLX protein) and PIGG." (PMID 29386520, 2018).
tumor (5 papers, 2020 to 2024). "SLC8B1 downregulation causes mtCa2+ overload, which increased mitochondrial reactive oxygen species accumulation with consequent HIF1 α signaling activation, leading to the metastasis of SLC8B1-null tumor cells." (PMID 39006025, 2024). "(B) RT-qPCR analysis of SLC8B1 mRNA in tumor tissues (n = 30) and adjacent normal tissues (n = 30) of CRC patients from Penn State University Hospital." (PMID 32914752, 2020). "NA = stage not known (G) RT-qPCR analysis of SLC8B1 mRNA in combined stage I/II (n = 9) and stage III/IV (n = 20) CRC tumor samples compared to their adjacent normal tissues obtained from Penn State University hospital." (PMID 32914752, 2020).
neurodegenerative disease (4 papers, 2019 to 2023). A disorder of the central nervous system characterized by gradual and progressive loss of neural tissue and neurologic function. "Mitochondrial calcium overload contributes to neurodegenerative diseases as it was demonstrated in a neuronal-specific deletion model of SLC8B1 in mice, however, to our knowledge, no DC-specific role of SLC8B1 has yet been described." (PMID 38077407, 2023).
SLC8B1 also shares sentences with these, for which no sentence is quoted: heart failure (8 papers); colorectal cancer (5); Parkinson disease (5); cognitive decline (4); Cognitive impairment (3); infection (2); ischemia (2); neurological diseases (2); oral cancer (2); osteosarcoma (2); psychosis (2); adenocarcinoma (1); adenoma (1); asthma (1); atherosclerosis (1); breast carcinoma (1); cardiac disease (1); colitis (1); colorectal (1); colorectal adenocarcinoma (1); diabetes (1); endothelial dysfunction (1); fibrosis (1); Friedreich ataxia (1); glioblastoma (1); glioma (1); hearing loss (1); hyperuricemia (1); insulinoma (1); melanoma (1).
A further 7 diseases each share a sentence with SLC8B1 in 1 paper.